ICAM1 (intercellular adhesion molecule 1)
Diseases named in the same sentence as ICAM1 in open-access papers (continued):
Sharing a sentence is not in itself a finding about the gene and the disease.
viral infection (67 papers, 2005 to 2026). "Other genes intimately involved in the host response to viral infection include the ICAM1 and IFITM3 genes that encode cell adhesion molecules." (PMID 37504295, 2023). "These T cells provided critical help for the viral Ag-specific ICAM-1/2-/- B-2 cells that entered the ICAM deficient MedLNs in response to viral infection." (PMID 36895258, 2022). "Apart from SP-A and SP-D deficiency, the increased ICAM-1 protein levels were also reported to aggravate virus infection." (PMID 23227098, 2012). "Chronic bacterial colonisation could contribute to the increased susceptibility of COPD patients to viral infection, for example, by increasing ICAM-1 expression on the surface of the bronchial epithelial cells." (PMID 27178410, 2016). "Furthermore, environmental triggers like viral infections, particularly those caused by rhinovirus, exacerbate eosinophilic activity by upregulating adhesion molecules such as intercellular adhesion molecule-1 (ICAM-1) on epithelial cells." (PMID 39518415, 2024). "During viral infection, RV-A16 receptor ICAM-1 was up-regulated by PA and IFN-γ, which was also significantly down-regulated by 2-DG." (PMID 41008536, 2025). "An enhancement of Icam1 expression most often occurs upon acute inflammation and viral infections involving functionally active neutrophils with an increased ability to migrate, which can be additional factor of observed persisting inflammation." (PMID 40001601, 2025). "Up-regulation of ICAM-1 is, thus, important in common cold virus infection, also in margination, migration, and retention of circulating neutrophils, monocytes, lymphocytes, and eosinophils in airway and lung tissues." (PMID 39598462, 2024). "The qRT-PCR results indicated an up-regulation trend for DDX58, STAT1, and MX1, while IRAK1, MAPK11, RELA, and ICAM1 exhibited a down-regulation trend as the duration of the viral infection increased." (PMID 38673764, 2024). "ICAM1 regulates the movement of white blood cells, adhesion to blood vessels, and inflammation; in some viral infections, it has been recognized as the receptor to release virus RNA in the patient’s host cells, thus exacerbating the infection." (PMID 39202454, 2024). "ICAM-1 is central to the cell-contact-mediated mechanism of viral infection, as it promotes adhesion between effector and target cells and promotes formation of a virological synapse." (PMID 36827461, 2023). "Taken together, these data suggest that Pom’s effects on B7-2 and ICAM-1 upregulation in certain lymphoma lines requires the presence of virus infection." (PMID 37463943, 2023). "Our study revealed upregulation of ICAM-1 expression in IAV-infected ECs, indicating that virus infection activates ECs, and increasing the risk of cardiovascular dysfunction in influenza patients." (PMID 36082118, 2022). "Among them, ICAM1 (a well-known gene involved in viral infection and cardiovascular disease) expression has been demonstrated to be consistent with IL-6 expression in mouse macrophages." (PMID 33520118, 2021). "The ICAM-1 protein plays a key role in controlling viral infection in lung epithelial cells during the early stages of infection, influencing the migration of immune effector cells into the airways." (PMID 33301474, 2020). "Pretreatment with tulobuterol reduced the expression of ICAM-1, the receptor for the major group RVs, and increased the minimum dose of RV14 necessary to cause viral infection." (PMID 24303127, 2013). "Taking this together with the maintained IP-10 and IFN responses, it is unlikely inhibition of IL-1RI signaling mediates its effects by downregulation of ICAM-1 and reduced viral infection." (PMID 23723976, 2013). "L-carbocisteine also inhibits RS viral infection through the reduced expression of an RS virus receptor, ICAM-1." (PMID 22966430, 2012).
viral infection (continued). "The modulation of oxidative stress observed here can explain the inhibition of ICAM1 overexpression and the subsequent inhibition of viral infection of differentiated NHBECs." (PMID 23118923, 2012). "Thus, to reduce viral infections in obese subjects with type 1 inflammation, potential therapeutics targeting viral entry via ICAM-1 and viral replication induced by increased glycolysis/PPP should be considered for future studies." (PMID 41008536, 2025). "Azelastine was furthermore found to inhibit inflammation and intracellular adhesion molecule-1 (ICAM-1) upregulation induced by viral infections, effects that may contribute to the antiviral activity observed also against non-coronaviruses." (PMID 39772221, 2024). "ICAM-1 expression is constitutively low at the surface of ECs and may be upregulated in response to stimuli, such as viral infection, oxidative stress, and pro-inflammatory cytokines, including interleukin-1β (IL1β), TNF-α, and interferon-γ (IFN-γ)." (PMID 35062347, 2022). "The upregulated genes associated strongly with microglial activation and included antigen presentation genes (Tap1, B2m) and activation genes (Ccl12, IL-34 and Icam1) that occur in neurodegenerative disease, brain injury and viral infection, and are NF-κB regulated." (PMID 35464428, 2022). "The observation that both OBLs decreased RV-16-induced ICAM-1 expression might be interpreted as a protective function against viral infection." (PMID 33613792, 2021). "In conclusion, these results indicated that ICAM-1 might play an important role in mucosal immune response to viral infection in teleost fish." (PMID 34489953, 2021). "In this study, we demonstrated that HPMEC could be infected by H1N1 virus, and responded to viral infection to produce pro-inflammatory mediators including ICAM1." (PMID 28399143, 2017). "Taken together, these findings support the hypothesis that Muc-1 influences local NF-κB-mediated proinflammatory signaling, which leads to de novo expression of ICAM-1 in the vicinity of viral infection, which in turn enhances macrophage infiltration into the infected and inflamed areas." (PMID 31337812, 2019). "Our data showing more ICAM-1 by PA and IFN-γ during viral infection are in line with previous studies and provide an additional mechanism of increased viral entry." (PMID 41008536, 2025). "Previous studies have indicated that most HRV-A serotypes enter the cell via ICAM-1 or bind low-density lipoprotein receptor (LDL-R), which is potentially the critical step for viral infection." (PMID 39529970, 2024). "It was interesting to note that TNR6 continued to be upregulated in the recovery phase of viral infection along with its death ligand TNFL6 and ICAM1." (PMID 37831367, 2024). "With the cutoff threshold of ≤ 0.05 p value and 1.41-fold change, ICAM1 and CCL27 were the most significantly increased and decreased proteins, respectively, in the viral infection category." (PMID 37831367, 2024). "The expression of ICAM-1 is also activated by the HTLV-1 protein, Tax, which plays an essential role in viral infection." (PMID 37375521, 2023). "The viral protein, HBZ, was found to enhance HTLV-1 infection through transcriptional activation of ICAM1 and MYOF, two genes that facilitate viral infection." (PMID 37375521, 2023). "In addition, viral infection may compromise the epithelial barrier, alter the mucosal surface environment, degrade antimicrobial peptides, and expose adhesion receptors, such as ICAM-1, CEACAM-1, platelet-activating factor receptor (PAFr), and Fn, thereby facilitating bacterial adhesion and growth." (PMID 37065141, 2023). "The 8-gene signature included three genes over-expressed in bacterial infections (SMARCD3, ICAM1, EBI3; “bacterial genes”) and five over-expressed in viral infections (JUP, SUCLG2, IFI27, FCER1A, HESX1; “viral genes”)." (PMID 36543117, 2022).
viral infection (continued). "We found that mRNAs of ICAM-1, VCAM-1, E-selectin, fractalkine (CX3CL1), IL-8, TLR3, and Bcl2-A1 were activated by H1N1 viral infection and suppressed by TSL-1 treatment." (PMID 24073006, 2013). "Nevertheless, the culture and infection/mock treatment significantly increased the expression of Fas and ICAM-1 transcript regardless of the viral infection." (PMID 39144143, 2024). "As viral infection and replication occur in tumor, using non-tumor-bearing Hu/Mu ICAM-1 transgenic mice enable us to characterize the pharmacokinetics of OV without the interfering impact of its own replication." (PMID 37771727, 2023). "This activity may contribute to the therapeutic effects of Pom in these tumors, since an effective T-cell immune response against virus infection requires expression of MHC-I and/or co-stimulatory molecules such as B7-2 and ICAM-1 on target cells." (PMID 37463943, 2023). "Since these sIFs have strong connections to inflammatory diseases and viral infections, it is unsurprising to see elevated fecal levels in PLWH but levels of four sIFs (GM-CSF, ICAM-1, IL-7 and IL-12/23) were similarly elevated in MSM-SN compared to non-MSM-SN." (PMID 36605218, 2022). "ICAM-1 expression on alveolar epithelial cells is also not critical for leukocyte entry into the bronchoalveolar spaces during this viral infection." (PMID 36895258, 2022). "We also proved infected HPMEC treated with CYM5442 produced decreased levels of ICAM1 compared to infected cells treated with vehicle, suggesting the activation of S1PR1 is an important regulatory pathway for inflammation in lungs induced by viral infection." (PMID 28399143, 2017). "In agreement with these publications, we demonstrated here the specific S1PR1 agonist CYM5442 decreased the upregulated ICAM1 in endothelial cells upon H1N1 virus infection, indicating the regulatory functions of S1PR1 in endothelial cells also apply in virus infection." (PMID 28399143, 2017). "In addition, ICAM-1 is naturally incorporated into HIV-1 particles, which promotes virus infection by stabilizing virus adhesion to LFA-1 positive cells." (PMID 24489846, 2014). "Viral infections also enhance the production of inflammatory mediators and substances in airway epithelial cells, mast cells, and other inflammatory cells, such as IL-1, IL-6, IL-8, GM-CSF, RANTES, histamine, and intercellular adhesion molecule-1." (PMID 22966430, 2012). "The pattern of adult and neonatal ICAM-1 protein expression during the course of viral infection was similar to ICAM-1 mRNA expression (data not shown)." (PMID 22185352, 2011). "The viral infection rates that are seen following exposure to HIV-1 either lacking or bearing host-derived ICAM-1 are very low at the two time points studied in the microarray experiment (i.e. 8 and 24 h post-infection)." (PMID 19146679, 2009). "The activation of this factor during early stages of viral infection leads to the expression of several immune response genes; such as pro-inflammatory cytokines (IFN-β, TNF-α, IL-6, IL-8), chemokines (RANTES) and adhesion molecules (ICAM-1, VCAM-1)." (PMID 17971236, 2007). "However, excessive IFN-γ may promote viral infection and pro-inflammatory responses in airway epithelial cells in part through up-regulation of viral receptors such as ACE2 for SARS-CoV-2 and intercellular adhesion molecule 1 (ICAM-1) for RV-A16." (PMID 41008536, 2025). "However, excessive IFN-γ may promote viral infection and pro-inflammatory responses in epithelial cells in part through up-regulation of viral receptors such as ACE2 for SARS-CoV-2 and ICAM-1 for RV16." (PMID 41008536, 2025). "Moreover, increased bacterial adhesion may be mediated not only by virus infection but also by pro-inflammatory cytokines such as IL-6, IL-1α, and TNF-α, which upregulate receptors like ICAM-1, PAFr, and CEACAM1." (PMID 40520162, 2025).
viral infection (continued). "Additionally, the upregulation of ICAM-1 and CD47 at 24 hpi was blocked, confirming the involvement of the NF-κB pathway in mediating CD47 upregulation in airway epithelial cells during viral infection." (PMID 38693120, 2024). "Furthermore, during viral infection, the presence of ICAM-1 or of ICAM-2 on all lung capillaries is also not required for neutrophil or NK cell emigration into the alveolar space." (PMID 36895258, 2022). "Therefore, it was speculated that, in the process of viral infection, B4GALT5 up-regulated the expression of antigen presenting molecules (MHC I, II) and adhesion molecules (LFA-1, ICAM-1) to strengthen the monitoring and presenting of the virus." (PMID 29546034, 2018). "Therefore, the upregulation of ICAM-1 in response to HIV exposure not only promotes immune cell activation and inflammation which can further local damage, but also has the potential to help propagate viral infection of other cells." (PMID 26930653, 2016). "For example, the expression of the adhesion molecule ICAM-1 is increased in the bronchial epithelium in mild/moderate stable COPD in comparison with both control nonsmokers and current smokers and may play a role in the T cell epithelial adhesion and T cell-mediated response to viral infections." (PMID 27178410, 2016). "These staining results suggest that the entry of virus specific effector T cell egressing the MedLNs on their way to the bronchial mucosa during viral infection, likely involves VCAM-1 rather than ICAM-1 and ICAM-2 mediated adhesions." (PMID 36895258, 2022). "Although not studied clinically and not in the context of HRVs, the downregulation of ICAM-1 by ICAM-1 siRNA on human bronchial epithelial cells resulted in alteration of influenza virus copy numbers, suggesting the crucial role of ICAM-1 in this viral infection." (PMID 35316427, 2022).
gastric cancer (63 papers, 1997 to 2025). A primary or metastatic malignant neoplasm involving the stomach. "In one study, ICAM-1 expression was significantly associated with advanced stages of gastric cancer and poorer survival rates in human patients." (PMID 39911389, 2025). "On one hand, soluble ICAM1 released from the cell surface causes local immunosuppression in patients with gastric cancer." (PMID 37671167, 2023). "The emergence of gastric cancer is linked to ICAM1 levels, and hence ICAM1 can potentially be a biomarker for early diagnosis and prognosis of gastric cancer." (PMID 37671167, 2023). "ICAM1 has been linked to the pathophysiology of a number of autoimmune diseases and inflammatory syndromes, including gastric cancer, multiple sclerosis, and neuromyelitis optica." (PMID 37644514, 2023). "ICAM-1 has been implicated in adhesion of colorectal, pancreatic, and gastric cancer cells to the peritoneal mesothelium and the progression of carcinomatosis." (PMID 31803630, 2019). "Notably, the association between Icam-1 and gastric cancer metastasis has been confirmed through numerous clinical and pathological tissue studies." (PMID 38463490, 2024). "ICAM-1 expression was expressed in half of a gastric patient collective (49.0% of 108 gastric cancer patients), and its expression levels were associated with a more advanced stage of gastric cancer and lymph node metastasis." (PMID 30657059, 2019). "Previously, we described the presence of gastric cancer stem cells with the immunophenotype CD24+CD44+CD326+ICAM1+ in the gastric tissue of gastric cancer patients and some cell lines, including AGS." (PMID 39201551, 2024). "In the aggressive gastric cancer model of Hs 746T, the activity of ICAM-1 CAR T cells was mostly modest, despite a substantial expansion of CAR T cells within the tumor." (PMID 38550578, 2024). "Previously, our research group reported a GCSC immunophenotype (CD24+CD44+CD326+ICAM1+) in gastric cancer patients." (PMID 39201551, 2024). "Our research group identified gastric cancer stem cells (GCSCs) with the CD24+CD44+CD326+ICAM1+ immunophenotype isolated from gastric cancer patients." (PMID 39201551, 2024). "In our group, we identified a gastric cancer stem cell (GCSC) subpopulation with the CD24+CD44+CD326+ICAM1+ immunophenotype in patients with gastric cancer." (PMID 39201551, 2024). "We previously demonstrated the distinct expression of ICAM1 between gastric cancer patients and healthy volunteers, suggesting its potential as a therapeutic target." (PMID 39201551, 2024). "It was also reported that ICAM-1's production have been decreased in stomach cancer which is correlated to lymphatic metastasis." (PMID 39050471, 2024). "To this end, we performed longitudinal PET-CT imaging of ICAM-1 CAR T cells using 18F-NOTA-Octreotide in a Hs 746T gastric cancer model, where tumor cells lack overexpression of SSTR2 on their surfaces." (PMID 38550578, 2024). "In a xenograft animal model of gastric cancer, monotherapy with either ICAM-1-specific CAR-T cells or paclitaxel, a cytotoxic drug commonly used in gastric cancer, reduced the tumor burden but did not induce long-term survival of tumor-bearing mice." (PMID 36768665, 2023). "More recently, it has been shown that ICAM-1 CAR-T cells alone or in combination with CAR activation-dependent interleukin (IL)-12 release or paclitaxel, improve the outcome of advanced gastric cancer patients expressing ICAM-1." (PMID 36831396, 2023). "ICAM-1, secreted from the omental tissue, increased the migratory and invasive properties of gastric cancer cells in vitro." (PMID 36674743, 2023). "In our study, a significant reduction in ICAM-1 concentration in AGS gastric cancer cells was observed after 24 h of incubation with trastuzumab and novel Les-4367." (PMID 37047765, 2023).